ALK (ALK receptor tyrosine kinase)
Diseases named in the same sentence as ALK in open-access papers (continued):
Sharing a sentence is not in itself a finding about the gene and the disease.
lung adenocarcinoma (continued). "As EML4-ALK fusion is not as frequent as EGFR gene mutation, it would be important to efficiently and accurately identify those lung adenocarcinomas that harbor ALK rearrangements in clinical practice to guide the appropriate therapy." (PMID 24403104, 2014). "We therefore conducted of the present genomic profiling of lung adenocarcinomas with and without ALK fusion." (PMID 23289484, 2013). "In addition, 62.79% (n = 27/43) of patients harboring ALK alterations were never smokers and 86.05% (n = 37/43) were diagnosed with lung adenocarcinoma." (PMID 39807831, 2025). "If effective, this would indicate that the metastases were from ALK-positive lung adenocarcinoma; if not, they could be from LCNEC, leading to a timely shift to other treatments as needed." (PMID 39723252, 2024). "Notably, the patient survived 12 months without experiencing adverse events, a rare occurrence in ALK-rearranged lung adenocarcinoma cases." (PMID 38698976, 2024). "Despite the potential benefits of inhibition of ALK in patients with SDC with rearranged HNRNPH3-ALK tumors, established knowledge of lung adenocarcinoma, a cancer with a similar genetic makeup, may guide treatment decisions in SDC with genetically similar tumors." (PMID 38966479, 2024). "After completing a staging examination, she was diagnosed with a right lung adenocarcinoma with multiple metastases to the liver, lungs, hilum, and mediastinal lymph nodes (cT3N3M1c IVB [American Joint Committee on Cancer, version 8], EGFR/ROS/ALK/PD-L1-negative)." (PMID 38961982, 2024). "In addition to STRN-ALK fusion, ALK gene rearrangements may also lead to novel fusion of ALK and SLMAP genes, making SLMAP a potential marker for treating lung adenocarcinoma." (PMID 38201504, 2023). "Finally, the TCGA lung adenocarcinoma (LUAD) database was consulted to study the expression of ACE2 in EGFR- and KRAS-mutant samples and ACE2 expression was correlated with EGFR/HER, RAS, BRAF, ROS1, ALK, and MET mRNA expression." (PMID 36077610, 2022). "Lung adenocarcinoma is more likely to develop in women and those without a history of smoking, in which some targetable gene mutations including growth factor receptor (EGFR), anaplastic lymphoma kinase (ALK), BRAF, and ROS1 were positively expressed." (PMID 35187162, 2022). "Notably, mutations in ALK and PTEN are concordant in a range of tumor types, including lung adenocarcinoma, endometrial cancer, colorectal cancer, and triple‐negative breast cancer." (PMID 36128740, 2022). "In multivariate analysis adjusted for age, sex, smoking history, stage, surgical mode, and visceral pleural invasion, the CTNNB1 mutation and fusion genes (ALK, ROS1, RET) were negative prognostic factors for recurrence in early-stage lung adenocarcinoma (HR 4.47, p = 0.001; HR 2.73, p = 0.009)." (PMID 33140254, 2021). "The comparison of mixed-IMA and pure-IMA showed that there was no statistical difference in the frequency of EGFR or ALK variations, suggesting that these gene-level changes might happen in the entire tumor when lung adenocarcinoma harbors mucinous components." (PMID 33505917, 2020). "Pemetrexed/carboplatin plus anlotinib could be considered for patients with EGFR wild-type, ALK-negative lung adenocarcinoma, and BM." (PMID 32899099, 2020). "Moreover, the co-existence of EGFR gene mutations, ALK gene fusions, and ROS1 gene rearrangements has been reported in a few lung adenocarcinoma cases, but the co-alteration of ROS1, EGFR, and EML4-ALK in MPA remains unclear." (PMID 32677962, 2020). "Patient characteristics such as age, gender, smoking history, histology, performance status (PS) scores, and disease stage were similar across different ALK fusion groups, with majorities of the ALK-positive patients in our cohort were never smokers (81.6%) with lung adenocarcinoma (ADC; 96.0%)." (PMID 33363027, 2020).
lung adenocarcinoma (continued). "Driver genomic fusions [e.g. anaplastic lymphoma kinase (ALK), ROS1, and KIF5B-RET fusion, etc.] are thought not to be correlated with smoking-associated mutations and frequently served as driver events of smoking-signature-low lung adenocarcinomas." (PMID 33520689, 2020). "Five patients died in 10 months (m), 13 m, 8 m, 24 m and 1 m, after the diagnosis of ovarian metastasis from lung adenocarcinoma, including a patient harboring an ALK rearrangement (LTO_1) who did not undergo targeted therapy and had hypothyroidism for 3 years." (PMID 31455365, 2019). "Of course, there may be further A1 actionable variants in the cohort that we cannot identify at the DNA level (e.g., Her2neu or CD20 protein expression) and because we did not include fusion data in this analysis (e.g., ALK fusion in lung adenocarcinoma)." (PMID 29544535, 2018). "We compared the targeted next-generation-sequencing Oncomine Focus Assay (OFA; Thermo Fisher Scientific) with conventional ALK FISH and anti-Alk immunohistochemistry in a cohort of 52 lung adenocarcinomas (10 ALK rearranged, 18 non-ALK rearranged, and 24 untested cases)." (PMID 29580750, 2018). "In addition, we did not investigate the mutations of KRAS and ALK genes in EGFR-wt patients, which play a major role in the progression of lung adenocarcinoma and are mutually exclusive from EGFR gene mutations." (PMID 29383112, 2017). "We extended study of epigenetic priming to a patient-derived xenograft (PDX) model of lung adenocarcinoma, LX7, which has poorly differentiated histology, is negative for KRAS, EGFR (exons 18–21), and BRAF mutations, and is negative for ALK-fusions by cytogenetic analysis." (PMID 25474141, 2015). "In this study, we analyzed exome sequencing data from 16 EGFR/KRAS/ALK-negative tumors and paired normal samples and an applicable expansion cohort of 54 EGFR/KRAS-negative lung adenocarcinomas to identify novel somatic mutations in lung adenocarcinomas of never-smokers." (PMID 24576404, 2014). "Our results may also indicate that there is common and frequent chromosome abnormality in lung adenocarcinomas independent of ALK fusion, such as the 5p15.33 region, including TERT." (PMID 23289484, 2013). "Our findings suggest that initial screening with diagnostic immunohistochemistry for lung adenocarcinomas, followed by targeted PCR-based assays for common HER2 exon 20 insertions in non-smoking patients with wild-type EGFR/ALK status, could represent a cost-effective algorithm." (PMID 40526089, 2025). "Hence, due to intratumoral heterogeneity, the histological subtype diagnosis of lung adenocarcinoma may not be sufficient for the precise prediction of ALK rearrangement." (PMID 36823653, 2023). "The fact that most human tumour cells have telomerase activity indicates that its acquisition is vital for carcinogenesis and cell immortalization, and it might explain the reason why lung adenocarcinomas with or without ALK fusion shows similar frequency of copy number gain of this locus." (PMID 23289484, 2013). "Therefore, we considered that the diagnostic process of ALK rearrangement could be simplified as follows: screening by IHC with iAEP method followed by confirmatory FISH in EGFR and KRAS mutation-negative lung adenocarcinomas." (PMID 23936355, 2013). "CT-guided biopsy confirmed stage IV lung adenocarcinoma (TTF-1 and Napsin A positive, PD-L1 TPS 80%, EGFR/ALK/ROS1 negative)." (PMID 42022515, 2026). "We found that PD-L1 and HLA-I expression were adverse predictors of ALK rearrangement in lung adenocarcinomas, and that the abundance of CD8+ TILs in ALK-positive tumors was not different from that in ALK-negative tumors." (PMID 40376302, 2025). "With this background it appears unsurprising that in LTS patients, targetable alterations are much more frequent than among non-selected patients with adenocarcinoma of the lung (EGFR: 41 vs. 11%; ALK: 8 vs. 4.8%)." (PMID 37646818, 2024).
lung adenocarcinoma (continued). "Rearrangement of the ROS1 gene is observed in ~1–2% of patients NSCLC, particularly in non-smokers, those with lung adenocarcinomas, and patients without alterations in the EGFR or ALK genes." (PMID 38499647, 2024). "In this case report, we identified a novel non-reciprocal ALK fusion, ALK-C2orf91(intergenic) (A19: intergenic) and PPFIA1-ALK (P2:A20), by next-generation DNA sequencing in an advanced lung adenocarcinoma patient." (PMID 37706178, 2023). "A 73-year-old male patient was diagnosed with left lung adenocarcinoma T3N3M1b stage IVa, EGFR, ALK, ROS1 negative, PDL1 1–49%." (PMID 34521373, 2021). "We report a 71 year-old male patient diagnosed with advanced lung adenocarcinoma lacking key driving genes (EGFR, ALK, and ROS-1), and low expression of PD-L1 on tumor cells (10-15%)." (PMID 34993345, 2021). "Five hundred twenty-six patients of lung adenocarcinoma with PET/CT scan examination were enrolled, including 109 positive and 417 negative patients for ALK rearrangements from February 2016 to March 2019." (PMID 33738250, 2021). "A 73-year-old male patient was diagnosed with left lung adenocarcinoma IVa, EGFR, ALK, ROS1 negative." (PMID 34521373, 2021). "As none of the selected cell lines including the two lung adenocarcinoma lines NCI-H1993 and NCI-H441 harbored an ALK rearrangement, inhibitor effects were expected to occur primarily due to c-MET inhibition." (PMID 33596971, 2021). "Case Presentation: A 61-year-old female (never smoker) who initially presented with headache and dizziness was diagnosed with lung adenocarcinoma with multiple brain metastasis (cT2aN3M1b stage IV), and was negative for EGFR and ALK." (PMID 32351894, 2020). "ALK translocations, detected in 3–7% of non-selected NSCLC cohorts, are reported to occur more commonly in non-smokers, lung adenocarcinomas and non-Asian vs. Asian populations." (PMID 31386689, 2019). "Here, we describe a 57-year-old man who was diagnosed with stage IIIB lung adenocarcinoma and EGFR/KRAS/ALK-negative tumors." (PMID 29361925, 2018). "For example, KRAS mutations are frequently detected in lung adenocarcinomas in smokers, whereas genetic alterations in EGFR, ALK, ROS1, and RET are frequently detected in lung adenocarcinomas in non-smokers." (PMID 28894699, 2017). "In this study, we aimed to perform CGP on tumor specimens from patients with lung adenocarcinomas who tested negative for EGFR, KRAS and ALK previously at our institution." (PMID 26992220, 2016). "Our findings also confirmed the view that ALK rearrangements are more common in patients at advanced NSCLC and in patients with lung adenocarcinoma than with non-adenocarcinoma especially squamous cell carcinoma." (PMID 24959902, 2014). "Anaplastic lymphoma kinase fusion genes, resulting in ALK fusion proteins, are present in 3–5% of lung adenocarcinomas, commonly in never smokers and younger patients." (PMID 25505733, 2014). "Screening the 35% of never smokers with adenocarcinoma of the lung who will be both EGFR and KRAS wild type should, therefore, capture 92% of the ALK rearrangements contained within the never smoking adenocarcinoma population." (PMID 22374459, 2012). "In addition, 126 ALK‐positive and 161 EGFR‐positive lung adenocarcinoma patients, excluding nonadenocarcinoma patients, were also analyzed." (PMID 38400801, 2024). "Two patients with lung adenocarcinoma were both EGFR negative, ALK negative and KRAS negative." (PMID 34717570, 2021). "When only lung adenocarcinomas was concerned, NSCLC patients with stage I–III had lower yet nonsignificant incidence of ALK rearrangements than those with stage IV (OR = 0.53; 95% CI: 0.25–1.09; P = 0.09), with moderate heterogeneity (I2 = 52%) and evident publication bias (Nfs = −1.14)." (PMID 24959902, 2014). "However, ALK rearrangements have been found in only a small subset of NSCLC (2–5%) and lung adenocarcinoma (4–6%) cases, regardless of race." (PMID 23936355, 2013).
lung adenocarcinoma (continued). "From a heterogeneity standpoint, varied expression of lung adenocarcinoma markers, EMT, and tumor vasculature was observed across six different regions of the same tumor, suggesting that a single tumor biopsy would not provide a holistic assessment of this particular ALK‐rearranged cancer." (PMID 36423211, 2023). "Therefore, among the never-smoker lung adenocarcinoma cases without any known driver alterations in oncogenes such as EGFR, KRAS, ALK, etc., the estimated fraction of BCAR4 fusion could be approximately 2.2% (1/44)." (PMID 33204025, 2021).
neuroblastoma (571 papers, 2004 to 2026). Neuroblastoma (NB) is the most common solid, extracranial childhood tumor. "In cancer biology, midkine has been implicated in tumor progression in glioblastoma and neuroblastoma through ALK/NF-κB and Notch2/Hes1 signaling pathways." (PMID 41339619, 2025). "A 20x magnified image of a diagnostic neuroblastoma core with an H-score of 142.33 was provided for reference of near-average ALK staining in the patient tumor TMA." (PMID 40813394, 2025). "Recent ultradeep sequencing of diagnostic tumors from patients with high-risk neuroblastoma demonstrates that oncogenic aberrations are more prevalent than previously recognized, with 25% harboring an activating ALK mutation or gene amplification." (PMID 40813394, 2025). "The data suggest that high-risk neuroblastoma patients with ALK variants are a particularly high-risk group." (PMID 40115016, 2025). "For example, ALK G1128A, a G-loop mutation studied in the context of neuroblastoma, has intermediate oncogenic activity compared to other ALK mutations, but there is not enough data to determine prognostic significance." (PMID 40831936, 2025). "ALK mutations or gene amplification are present in up to 15% of sporadic high-risk neuroblastomas, the most common somatic single-nucleotide variant in neuroblastoma and the most frequently mutated oncogene." (PMID 40115016, 2025). "Relapsed high-risk neuroblastomas (NBLs) are enriched for targetable mutations in ALK and RAS-MAPK pathways, yet the prognostic effect of these aberrations and relevance of subclonal mutations at diagnosis remain undefined." (PMID 40036726, 2025). "Activating point mutations and gene amplification of ALK in neuroblastoma have also been implicated in enhanced tumor aggressiveness and therapeutic resistance." (PMID 41614760, 2025). "The actionable point mutations are more frequently presented in neuroblastoma (ALK missense mutations) and prevail in high-risk and relapse tumors, warranting TT with ALK inhibitors." (PMID 41373618, 2025). "In the COG high-risk neuroblastoma population, a poorer prognosis has also been observed in cases with ALK variants or ALK amplification." (PMID 40115016, 2025). "ALK (anaplastic lymphoma kinase) mutations have also been identified as drivers of tumor development in both familial and sporadic cases of neuroblastoma." (PMID 39720601, 2025). "Primary resistance to inhibitors such as crizotinib is commonly associated with ALK hotspot mutations (e.g., F1174L and F1245C) in neuroblastomas, hence the term refractory ALK variants for such variants." (PMID 40115016, 2025). "In neuroblastoma, ALK aberrations are predominantly point mutations within the kinase domain, with R1275Q and F1174L representing the most frequent variants." (PMID 41614760, 2025). "The data suggest that MYCN gene amplification is often accompanied by ALK mutation activation, and the two synergistically initiate and promote the development of neuroblastoma." (PMID 40115016, 2025). "Targeting drug-resistant ALK mutations, the third-generation ALK tyrosine kinase inhibitor loratinib exerted unprecedented preclinical activity as a single agent in a xenograft model of neuroblastoma patients with three hotspot mutations." (PMID 40115016, 2025). "The oncogenic mechanisms of ALK involve increasing gene-copy number, activating point mutations (mainly in neuroblastoma), and formation of fusion-ALK proteins." (PMID 38465731, 2024). "Germline mutations in the anaplastic lymphoma kinase (ALK) gene are found in 80% of familial cases, while around 10% of neuroblastoma cases display somatic ALK mutations." (PMID 38791942, 2024). "Treatment of neuroblastoma cells with ALK inhibitors enhanced total and surface expression of ALK, especially in ALK‐mutated cells." (PMID 38877641, 2024).